AQP1 (aquaporin 1 (Colton blood group))
Description:
Forms a water channel that facilitates the transport of water across cell membranes, playing a crucial role in water homeostasis in various tissues. Could also be permeable to small solutes including hydrogen peroxide, glycerol and gases such as amonnia (NH3), nitric oxide (NO) and carbon dioxide (CO2). Recruited to the ankyrin-1 complex, a multiprotein complex of the erythrocyte membrane, it could be part of a CO2 metabolon, linking facilitated diffusion of CO2 across the membrane, anion exchange of Cl(-)/HCO3(-) and interconversion of dissolved CO2 and carbonic acid in the cytosol. In vitro, it shows non-selective gated cation channel activity and may be permeable to cations like K(+) and Na(+) in vivo.
Synonyms: CHIP28; AQP-CHIP; CO
Tractability: Small molecule: a structure with a bound ligand is known; it has a high-quality binding pocket. Antibody: UniProt places it where antibodies can reach, with high confidence; its Gene Ontology location is reachable by antibodies, with high confidence; UniProt predicts a signal peptide or a membrane-spanning region; the Human Protein Atlas places it where antibodies can reach. PROTAC: a small molecule that binds it is known.
Target class: Ion channel; Other ion channel; Aquaporin; Water-specific aquaporin
Safety:
Unwanted effects reported when the protein is acted on. In parentheses: how it was acted on, where the effect was seen, and who reports it.
alopecia (source: ClinPGx)
anemia (source: ClinPGx)
leukopenia (source: ClinPGx)
thrombocytopenia (source: ClinPGx)
Gene: Protein-coding gene on chromosome 7 (30,911,720 to 30,925,517, forward strand). Ensembl gene ENSG00000240583.
Subcellular location: Cell membrane
Subcellular location (Human Protein Atlas): Plasma membrane
Pathways (Reactome):
Transport of small molecules: Erythrocytes take up carbon dioxide and release oxygen; Erythrocytes take up oxygen and release carbon dioxide; Passive transport by Aquaporins; Vasopressin regulates renal water homeostasis via Aquaporins
Developmental Biology: Developmental Lineage of Pancreatic Ductal Cells
Gene Ontology:
Molecular function: ammonium channel activity; carbon dioxide transmembrane transporter activity; glycerol transmembrane transporter activity; hydrogen peroxide channel activity; identical protein binding; intracellularly cGMP-activated cation channel activity; nitric oxide transmembrane transporter activity; potassium channel activity; protein binding; transmembrane transporter activity; water channel activity; water transmembrane transporter activity; potassium ion transmembrane transporter activity; channel activity; ephrin receptor binding
Biological process: ammonium transmembrane transport; carbon dioxide transmembrane transport; carbon dioxide transport; cell volume homeostasis; cellular homeostasis; cellular hyperosmotic response; cellular response to cAMP; cellular response to copper ion; cellular response to dexamethasone stimulus; cellular response to hydrogen peroxide; cellular response to hypoxia; cellular response to mechanical stimulus; cellular response to mercury ion; cellular response to nitric oxide; cellular response to retinoic acid; cellular response to salt stress; cellular response to UV; cerebrospinal fluid secretion; defense response to Gram-negative bacterium; establishment or maintenance of actin cytoskeleton polarity; glycerol transmembrane transport; intracellular water homeostasis; lateral ventricle development; multicellular organismal-level water homeostasis; negative regulation of apoptotic process; and 20 more
Cellular component: ankyrin-1 complex; apical part of cell; apical plasma membrane; basal plasma membrane; basolateral plasma membrane; brush border; brush border membrane; cytoplasm; extracellular exosome; nuclear membrane; nucleus; plasma membrane; sarcolemma; axon; membrane
Genetic constraint (gnomAD): Loss-of-function variants: 11 observed, 19.91 expected, observed/expected ratio (o/e) 0.55, 90% interval 0.35 to 0.92. The upper end of that interval is the gene's LOEUF score, 0.92, which puts it in group 3 of 6, group 1 being the genes least tolerant of losing a copy. Missense variants: 320 observed, 379.01 expected, observed/expected ratio (o/e) 0.84, 90% interval 0.77 to 0.93. Synonymous variants: 159 observed, 172.27 expected, observed/expected ratio (o/e) 0.92, 90% interval 0.81 to 1.05.
Gene-disease validity (ClinGen):
ClinGen rates the evidence that AQP1 causes each of these diseases.
pulmonary arterial hypertension (autosomal dominant): Limited. Pulmonary arterial hypertension (PAH) is a group of diseases characterized by mean pulmonary artery pressure >20 mmHg and elevated pulmonary arterial resistance leading to right heart failure.
Homologues: Orthologues: chimpanzee AQP1 (99% identical), mouse Aqp1 (94% identical), dog AQP1 (94% identical), pig AQP1 (93% identical), rat Aqp1 (93% identical), guinea pig AQP1 (93% identical), tropical clawed frog aqp1 (77% identical), zebrafish aqp1a.1 (59% identical), zebrafish aqp1a.2 (56% identical), Drosophila melanogaster Eglp3 (29% identical), Drosophila melanogaster Eglp2 (26% identical), Drosophila melanogaster Eglp4 (25% identical), and 1 more. Paralogues in human: AQP5 (44% identical), MIP (44% identical), AQP2 (44% identical), AQP4 (43% identical), AQP6 (41% identical), AQP8 (25% identical), AQP3 (24% identical), AQP7 (24% identical), AQP7B (23% identical), AQP10 (22% identical), AQP9 (21% identical).
Diseases named in the same sentence as AQP1 in open-access papers:
AQP1 is named in the same sentence as 346 diseases in open-access papers, as found by Europe PMC text mining. Sharing a sentence is not in itself a finding about the gene and the disease. The quoted sentences say what the papers report.
breast cancer (56 papers, 2002 to 2025). A primary or metastatic malignant neoplasm involving the breast. "Some studies have shown that overexpression of AQP1 is associated with the progression of breast cancer." (PMID 38791252, 2024). "Oestrogen-mediated AQP1 overexpression in breast cancer is downregulated by microRNA-320, was linked to a poor prognosis for patients with breast cancer." (PMID 38336645, 2024). "Several aquaporins are overexpressed in breast cancer, and AQP1, AQP3 and AQP5 have been linked to spread to lymph nodes and poor prognosis." (PMID 37681917, 2023). "Otterbach’s group reported AQP1 expression was positive associated with poor survival, where high expression of AQP1 was positive associated with high tumor grade in breast cancer." (PMID 36803413, 2023). "AQP1 has been reported to be associated with a poor prognosis, especially in later stages of colon cancer, lung cancer and breast cancer." (PMID 33644043, 2021). "Especially in BC, AQP1 overexpression is significantly associated with poor prognosis in aggressive breast cancer." (PMID 32903818, 2020). "High levels of AQP1 protein were associated with the most aggressive subtypes of basal-like breast carcinomas." (PMID 32679804, 2020). "Clinically, AQP1 expression was increased in breast cancer compared to adjacent normal tissue, and high AQP1 expression was associated with TNBC and poorer progression-free and overall survival." (PMID 31574930, 2019). "In mouse models of breast carcinoma with lung metastasis, AQP1 deficiency decreased the expression of VEGFR2 leading to significantly reduced tumor mass and volume, microvasculature density, and the number of lung metastases." (PMID 30678106, 2019). "Furthermore, miR-320 negatively regulates AQP1 expression, and the downregulation of miR-320 and the upregulation of AQP1 are associated with worse prognosis in breast cancer patients." (PMID 38136293, 2023). "In particular, the high AQP1 expression has been associated with poor prognosis in numerous cancers, including ovarian carcinoma, lung cancer, prostate adenocarcinoma, brain tumors and breast cancer." (PMID 33807998, 2021). "This correlation was verified in studies with AQP1-null mice with melanoma and breast cancer as well as in colon and lung cancer cell lines." (PMID 39941100, 2025). "Overexpression of AQP1 promotes VM and metastasis in breast cancer, whereas its suppression inhibits VM, highlighting its critical role in tumor aggressiveness." (PMID 41463012, 2025). "miR-320 can reduce AQP1 expression in breast cancer, decreasing anthracycline chemosensitivity and impairing tumor proliferation, migration and invasion." (PMID 39941100, 2025). "Hu and Verkman showed that the AQP1 expression at the advancing end of migratory cells increased the motility of breast cancer 4 T1 and mouse carcinoma B16F10 cell lines in vitro." (PMID 38336645, 2024). "Breast cancer tumor cells actively utilize water for angiogenesis and AQP1 plays a vital role in water transport by tumor cells." (PMID 38791252, 2024). "There is evidence that these water channels are associated with increased cell proliferation and invasion and are therefore upregulated in breast cancer cells, making AQP1 a potential prognostic marker for breast cancer." (PMID 38296892, 2024). "Studies have shown that AQP1 is a key target of local invasion of breast cancer, involving in migration and invasion of breast cancer cells, and therefore targeting AQP1 offers promise for breast cancer treatment." (PMID 38670996, 2024). "In breast cancer, overexpression of AQP1, 3, 4, 5, and 7 correlates with proliferation, tumor type, grade, prognosis, and overall and relapse-free survival." (PMID 39123442, 2024). "The worst forms of basal-like breast carcinomas were found to have abnormally high amounts of the AQP1 protein." (PMID 38336645, 2024). "In conclusion, this study demonstrates that AQP1 is critical to the local invasion in breast cancer metastasis." (PMID 36803413, 2023).
breast cancer (continued). "We further validated the function of AQP1 in breast cancer local invasion in vivo using xenograft mouse model." (PMID 36803413, 2023). "Our study report here suggested a new molecular mechanism of AQP1 that promoted breast cancer local invasion." (PMID 36803413, 2023). "In conclusion, this study demonstrates that AQP1 is critical for the local invasion in breast cancer metastasis." (PMID 36803413, 2023). "A previous study performing transcriptomic analyses on breast cancer biopsies revealed increased mRNA expression of AQP1, AQP3, AQP5, AQP7, AQP9 and AQP11 when compared to overall median AQP levels in the biopsies." (PMID 37681917, 2023). "We randomly selected RNA-seq data of 15 cases with AQP1 high expression and 15 cases with AQP1 low expression from the 817 breast cancer patients to characterize the similarity between AQP1 and other 17 proteins in the two RNA-seq groups." (PMID 36803413, 2023). "Immunofluorescence staining revealed AQP1 co-localized with Rab1b in the perinuclear Golgi region of breast cancer cells." (PMID 36803413, 2023). "Transcriptomic analyses using the Human Protein Atlas database revealed higher mRNA levels of several AQPs in human breast cancer, namely AQP1, AQP3, AQP5, AQP7, AQP9 and AQP11, when compared to overall median AQP expression levels in the biopsies." (PMID 37681917, 2023). "These experiments supported that AQP1 had a primarily cytoplasmic location in breast cancer cells and that a high cytoplasmic expression of AQP1 contributed to breast cancer local invasion in vitro and in vivo." (PMID 36803413, 2023). "Here we identified the water channel protein AQP1 as a crucial target in breast cancer cell invasion." (PMID 36803413, 2023). "In order to explore the role of AQP1 in breast cancer prognosis, we assessed the overall survival time of the 194 IDC patients with complete clinical follow-up." (PMID 36803413, 2023). "Our previous study revealed that water channel protein AQP1 was mainly localized in the cytosol of breast cancer cells and promoted breast cancer progression." (PMID 36803413, 2023). "Functional cell experiments showed that the two primary breast cancer cell lines over-expressing AQP1 demonstrated increased migration and invasion abilities." (PMID 36803413, 2023). "Based on the RNA sequencing data from the 817 breast cancer samples in the TCGA database, we obtained AQP1- and ANXA2-related genes." (PMID 36803413, 2023). "AQP1 was shown to be a prognostic marker for poor outcomes in epithelial ovarian cancer and in highly invasive basal-like breast cancer." (PMID 37760476, 2023). "We sought to identify AQP1-dependent secreted proteins that induced breast cancer cell local invasion." (PMID 36803413, 2023). "Since endogenous AQP1 was undetectable in MDA-MB-231 cell lines, we utilized two primary breast cancer cell lines to investigate the function of AQP1." (PMID 36803413, 2023). "There were 76 proteins detected only in the AQP1-overexpressing group, including proteins reported to exert prosurvival and/or prometastatic activities in breast cancer, such as intercellular adhesion molecule 1 (ICAM1), cathepsin S (CTSS), and PLAT." (PMID 36803413, 2023). "The phosphorylation levels of AQP1 in breast cancer cells exhibiting a high cytoplasmic pool were likely lower as compared to cells expressing mainly a plasma membrane pool of AQP1." (PMID 36803413, 2023). "Cytoplasmic staining of AQP1 was confirmed in two primary breast cancer cell lines, with localization consistent with AQP1 localization in the clinical samples and AQP1-overexpressing MDA-MB-231 cells." (PMID 36803413, 2023). "The present study focused on the molecular mechanisms of cytoplasmic AQP1 in promoting breast cancer development." (PMID 36803413, 2023). "Among the 110 low-cytoplasmic-AQP1-expressing samples, 21.8% (24/110) of breast cancer tissues showed positive ANXA2 membranous expression." (PMID 36803413, 2023).
breast cancer (continued). "Our previous reports indicated that the water channel protein AQP1 was localized dominantly in the cytoplasm of breast cancer cells, and expression of AQP1 was positively correlated with advanced pathological features of invasive ductal carcinoma (IDC)." (PMID 36803413, 2023). "AQP1 overexpression plays a key role in proliferation, migration, and invasion in several breast cancer subtypes." (PMID 36212456, 2022). "AQP1 localized to the cytoplasm of cancer cells of invasive breast cancer patients, and cytoplasmic expression of AQP1 promoted breast cancer and correlated with tumor size, distant metastasis, and histological grade." (PMID 36212456, 2022). "This association with chemotherapy sensitivity via AQP1 occurred not only in breast cancer but also in human bladder cancer cells, where AQP1 inhibition enhanced mitomycin C sensitivity, and also in colorectal and ovarian cancers." (PMID 36212456, 2022). "Using a panel of 155 female breast cancer tissues, AQP1 and HIF-1α expression were stained by immunohistochemistry and analyzed." (PMID 36212456, 2022). "Some miRNAs target AQP1 and, thus, reduce breast cancer progression, cell migration, and invasiveness." (PMID 36212456, 2022). "Immunohistochemical expression of AQP1 has been demonstrated as a prognostic biomarker in several solid tumours, including mesothelioma, breast cancer, colorectal cancer, brain tumours, prostate adenocarcinoma, lung adenocarcinoma, and ovarian cancer." (PMID 35328186, 2022). "Next, we outline the roles in breast cancer of AQP1, AQP3, AQP4, AQP5, and AQP7, which are the only AQPs that have begun to be characterized as having roles in breast cancer progression and as potential prognostic markers." (PMID 36212456, 2022). "Several follow-up reports have confirmed the expression of AQP1 among various human malignancies including brain tumors, hemangioblastomas, multiple myeloma, lung cancer, and breast cancer, expanding the expression of AQPs to multiple cancer types." (PMID 35847914, 2022). "Among patients with HIF1-positive and HIF1-negative breast cancer, the expression of AQP1 was found to be positively correlated with HIF expression." (PMID 35847914, 2022). "The expression pattern of AQP1 in breast cancer tissues, distinct from that in healthy tissues, suggests a possible relation between its cytoplasm localization and its function in breast cancer development." (PMID 32814878, 2021). "It has been shown that AQP1 furthers lung metastases in a breast cancer model and lead to an increased metastatic potential in melanoma and glioma." (PMID 33644043, 2021). "In breast cancer cells, a combination of both bacopasides, I which blocks the AQP1 ion channel, and II which blocks the AQP1 water pore, decreased invasion by up to 97%, an effect that was dependent on AQP1 expression." (PMID 34769339, 2021). "Our results also showed AQP1 and β-catenin co-immunoprecipitated with each other in breast cancer tissues and Flag-AQP1/MDA-MB-231 cells, respectively." (PMID 32814878, 2021). "The endogenous AQP1 expression was detectable in mouse kidney tissues and breast cancer tissues, but it was undetectable in parental MDA-MB-231, T47D, and MCF7 cell lines." (PMID 32814878, 2021). "The mRNA level of AQP1 was detected by RT-qPCR, and decreased expression of AQP1 was observed in miR-320a-3p/primary breast cancer cells." (PMID 32814878, 2021). "We selected 1218 breast cancer patients’ RNAseq data from TCGA to further explore how AQP1 modulated EPI sensitivity." (PMID 32814878, 2021). "As a consequence, AQP1 interacted with β-catenin in breast cancer cells, and only patients with both high expression of AQP1 and β-catenin presented the best outcomes in the anthracycline chemotherapy." (PMID 32814878, 2021). "It has been shown in an AQP1 knock-out breast cancer model that AQP1 gene deletion reduces breast tumor growth and lung metastasis." (PMID 33644043, 2021).